FOXO1 (forkhead box O1)
Diseases named in the same sentence as FOXO1 in open-access papers (continued):
Sharing a sentence is not in itself a finding about the gene and the disease.
tumor (continued). "This autophagy-inducing mechanism keeps FoxO1 inactive as a transcription factor in the cytoplasm but still inhibits the growth of tumor xenografts in nude mice." (PMID 36065306, 2022). "FOXO1 plays a key role in tumor growth inhibition by inducing growth arrest and apoptosis, while functional failure due to phosphorylation and proteasomal degradation has been related to cell malignancy." (PMID 36157053, 2022). "Although our study has proposed a novel functional miR-9-5p/FOXO1/CPEB3 FFL in the tumor growth of HCC, more complete studies are needed in future experiments to enhance the validation of the functional role of the FFL." (PMID 35805200, 2022). "The cell proliferation activity was progressively increased in presence of miR-bDNA nanostructures which confirms the reduced tumor suppression activity of FOXO1 and the downstream gene expression." (PMID 36539739, 2022). "HDAC inhibition enhances the expression of FOXO1, an onco-suppressor gene, thus suppressing tumor growth." (PMID 35053495, 2022). "Inhibition of AGK also led to enhanced efficacy of venetoclax for suppression of DLBCL tumor growth in vivo, which was dependent on FOXO1." (PMID 35910796, 2022). "MiR-9-5p had higher expression in tumor tissues compared to adjacent tissues, while FOXO1 and CPEB3 were expressed higher in adjacent tissues." (PMID 35805200, 2022). "It is furthermore reported that FOXO1 exerts its anti-tumor action by regulating the autophagy of tumor cells." (PMID 35126526, 2022). "We also found a significant correlation of FOXO1 mRNA level with Age (p = 0.008), age at first live birth (p = 0,003), tumor size (p = 0.05) and lymph node status (p = 0.01)." (PMID 35309123, 2022). "FOXO1 is a TF that acts as a tumor suppressor in regulating cell cycle, progression, differentiation, metabolism and survival." (PMID 35805200, 2022). "FOXO1 gene plays an important role in a variety of intracellular functions, including tumor suppression and cellular immune regulation." (PMID 36290822, 2022). "The transcription factor Fork-head box O1 (FoxO1) is an Akt substrate that plays a key role in tumor suppression by promoting transcriptional activation of p27kip." (PMID 35203272, 2022). "The miR-9-5p/FOXO1/CPEB3 FFL was associated with poor prognosis, and promoted cell growth and tumor progression of HCC in vitro and in vivo." (PMID 35805200, 2022). "XBP1-u then recruits FoxO1 to the 20S proteasome and degrades FoxO1 to inhibit autophagy, thereby suppressing tumor cell death." (PMID 35269888, 2022). "For example, cytosolic FOXO1 acts as a tumor suppressor or stress sensor by inducing autophagy in response to stress." (PMID 35361773, 2022). "At present, most scholars believed that FOXO1 played a tumor suppressor or tumor-promoting role completely depends on the tumor environment and disease stage in which it is located." (PMID 36290822, 2022). "Cytoplasmic FoxO3a and FoxO4 proteins were expressed in metastatic cells in the 4TLM group, similarly to FoxO1, and their expression levels were higher in the 4TLM compared to 67NR and tumor-free groups (p ˂ 0.05)." (PMID 36142156, 2022). "We found that treatment with 4sc‐202 potently reversed the EMT and thereby inhibited cell migration and invasion in vitro, in part by inducing expression of the FoxO1 tumor‐suppressor gene." (PMID 33772986, 2022). "Our findings, together with earlier studies, suggest that FOXO1 is required for B cell–originating tumor survival." (PMID 36282572, 2022). "Next, qRT-PCR analysis indicated that miR-9-5p expression was significantly decreased in tumor tissues after treatment with the combination of miR-9-5p inhibitor/FOXO1/CPEB3-shRNA (left)." (PMID 35805200, 2022). "Our data from ChIP experiments suggest that FoxO1 inhibited the invasion and metastasis of tumor cells by transcriptionally regulating the Twist1 promoter." (PMID 33772986, 2022).
tumor (continued). "This is interesting considering CdCl2 exposure tended to reduce FOXO1 expression which would result in tumour growth." (PMID 34905088, 2022). "The data indicate potential cardioprotective effects of preconditioning exercise on preserving cardiac structure and function, as well as regulating autophagic (beclin-1), inflammatory (TGF-β and MyD88), and atrophy (p-FOXO1) pathways during tumor bearing." (PMID 36531941, 2022). "Downstream of multiple oncogenes and tumor suppressor genes, decreased FOXO1 expression promotes tumor metastasis and is positively correlated with poor survival outcomes." (PMID 36585925, 2022). "The result showed that the deletion of FOXO1 and FOXO4 genes, and the increase in CNVs in the FOXO3 gene, were linked to tumor progression." (PMID 36555288, 2022). "Gain- and loss-of-function studies demonstrated that miR-9-5p promotes HCC tumor proliferation, while FOXO1 and CPEB3 inhibit hepatocarcinoma growth." (PMID 35805200, 2022). "As expected, tumor volumes (after day 17) and weights were significantly reduced with miR-9-5p silencing or FOXO1 overexpression, and tumor suppression was sustained after miR-9-5p silencing along with FOXO1 overexpression." (PMID 35805200, 2022). "Specifically, FoXO1, FoXO3, and Atrogin-1 mRNA levels and protein Murf-1 and Atrogin-1 were markedly increased in tumor-bearing mice compared to control." (PMID 35847939, 2022). "The accumulation of SKP2 subsequently leads to the degradation of tumor suppressors and apoptosis-inducing substrates, such as p21, p27, p130, and FOXO1, to promote tumor cell proliferation, growth, and survival." (PMID 35414786, 2022). "Expression of the RNA for FoXO1, FoXO3, and Atrogin-1, key genes in skeletal muscle proteolysis, were elevated along with the tumor development." (PMID 35847939, 2022). "Previous study reported that FoxO1 and FoxO3 were two major participants involved in regulating tumor cell survival under Trastuzumab treatment, therefore, we evaluated the expression states of FoxO1, FoxO3, FoxO4 and FoxO6." (PMID 35835735, 2022). "It has been extensively accepted that FOXO1 is one of the critical molecules regulating G1/S phase transition in tumor cells." (PMID 35723050, 2022). "The miR-96-5p expression level was increased along with tumor grade, and its target FoxO1 expression decreased along with tumor grade." (PMID 36556070, 2022). "There was a significant decrease in FOXO1 expression in KIRC tissues compared to that in non-tumor renal tissues at the RNA and protein levels." (PMID 36585925, 2022). "Compared to the control group, the percentages of cytoplasmic FOXO1 positive cells were reduced in shRNA AGK group tumor tissues, while the nuclear localizations of FOXO1 were significantly enhanced in shRNA AGK group." (PMID 35910796, 2022). "FOXO1 (forkhead boxO1) gene is a transcription factor regulating cell growth and a tumor suppressor gene." (PMID 35646647, 2022). "The bioinformatics analysis suggested that multiple tumor-related genes, including FoxO1, PTEN, and PDCD4 genes, have miR-21 binding sites." (PMID 36180486, 2022). "The downregulation of FOXO1 mRNA in our data links positively to the previous studies which state the tumor suppressive role of the FOXO1 gene in cancer progression." (PMID 35309123, 2022). "Our experimental results showed that CDM elicited anti-tumor effects by inhibiting HDAC3-mediated deacetylation of FOXO1." (PMID 35126526, 2022). "Previous studies have shown that the SIRT1/FoxO1/MDR1 pathway is hyperactivated in many tumours and mediates the multidrug resistance of tumour cells." (PMID 35022006, 2022). "Skp2 antagonizes the tumor suppression function of FOXO1 by promoting ubiquitination and degradation of the FOXO1 protein." (PMID 34068643, 2021). "Phosphorylation deactivates FoxO1 and prompts its dissociation from DNA and translocation from the nucleus to the cytoplasm, subsequently leading to the genesis of neoplasms and other diseases." (PMID 34295886, 2021).
tumor (continued). "The activation of PI3K-AKT signaling is common across many tumor types and the inactivation of FOXO1 in response to PI3K-AKT represents a common mechanism by which neoplastic cells prevent apoptosis and physiological cell cycle arrest." (PMID 33639972, 2021). "By immunofluorescence, FOXO1 was mostly restricted to the DAPI+ nuclei of CD31+ tumor endothelial cells in control and treated mice, attributable to the rapid degradation of cytoplasmic FOXO1." (PMID 34102002, 2021). "FOXO1 is a widely known tumor suppressor, owing to its role as a tumor motility inhibitor and tumor death inducer." (PMID 34635635, 2021). "In T cells, Sirt1 enhances the activity of Foxo1 by deacetylating Foxo1, and promotes the expression of Klf2 and Ccr7 genes, thereby improving the anti-tumor immune response of T cells." (PMID 34880761, 2021). "Forkhead transcription factors FOXO1 (Forkhead box O1) and FOXO3a (Forkhead box O3a) play a critical role in tumor suppression by inducing growth arrest and apoptosis." (PMID 34068643, 2021). "Of the FoxO family members, FoxO1 is the predominant isoform increased in skeletal muscle of both cachectic tumour‐bearing mice and cachectic cancer patients." (PMID 33527776, 2021). "FOXO1 is also essential in cell cycle regulation, stress resistance, and tumor suppression, all crucial in cancer stem cells." (PMID 34299605, 2021). "Several studies have reported that FOXO transcription factors are expressed in various cell types such as lung, breast, and prostate cells, leading to proliferation of tumor cells especially targeting FOXO1." (PMID 34833849, 2021). "PAX3:FOXO1 low cell states are characterized by more efficient adhesion, migration and tumor-propagating capacity." (PMID 34187933, 2021). "In Huh-6 cells and mouse tumor tissues, FoxO1 knockdown resulted in increased cell proliferation, migration, and invasion and active fatty acid metabolism." (PMID 34539243, 2021). "While the expression levels of miR-340 and FOXO1 genes in tumor samples displayed a significant reduction (p ≤ 0.001), the LGR5 gene presented a significant increase in expression (p ≤ 0.0001)." (PMID 33718760, 2021). "As an indicator of Ang1/2‐TIE2/p‐AKT signaling in the tumor vasculature, we examined the subcellular localization of the transcription factor Forkhead box protein O1 (FOXO1)." (PMID 34102002, 2021). "In conclusion, miR-552 serves as a tumor promoter in GC through targeting FOXO1 and regulating EMT and PI3K/AKT pathway." (PMID 34035814, 2021). "We further detected high Beclin 1 expression, low p62 accumulation (representing high autophagy activation), and increased FoxO1 staining in the tumors as well as in the nucleus of tumor tissues in amiodarone treatment group." (PMID 34737955, 2021). "Consistent with our observation that USP7 coordinated with the PRC2 complex is linked to downregulation of FOXO1, we showed that the expression level of FOXO1 is decreased and negatively associated with those of USP7 and EZH2 in various tumor tissue samples." (PMID 33849069, 2021). "Among them, FOXO1 is involved in a wide range of organismal functions and is considered as a tumor suppressor." (PMID 33849069, 2021). "FoxO1 is a known HCC tumor suppressor gene, and its expression is significantly down-regulated in HCC tissues." (PMID 33602225, 2021). "The upregulation of lncRNA ANCR in GC enhanced the migration and the invasion of the tumor, inhibiting macrophage M1 by targeting FOXO1 and by reducing the concentrations of IL-6 and IL-1β in the cells." (PMID 33522932, 2021). "In more than one cancer cell line, overexpression of miR-223 downregulated FOXO1 expression and suppressed tumor cell proliferation." (PMID 34857901, 2021).
tumor (continued). "To date, FoxO1 is considered a tumor suppressor, and its functions mainly depend on post-transcriptional modifications." (PMID 34295886, 2021). "Previous studies showed that FOXO1 is mediator of the production of inflammatory factors by macrophages favoring M1 macrophage polarization and hence, leading to anti-tumor environments." (PMID 33522932, 2021). "Treatment with Panobinostat causes an increase of the forkhead box protein O1 (FOXO1) target genes, which results in a decreased viability of tumor cells and prolonged survival in mouse models." (PMID 34066495, 2021). "FOXO1 was reported to be a tumor suppressor in a wide variety of cancers via anti-proliferation, pro-apoptosis, or cell cycle arrest." (PMID 34354043, 2021). "GAS5 also inhibited tumor inducer miR-196-5p, which led to suppressed tumor growth by positive regulation of tumor suppressors forkhead box protein O1 (FOXO1) and phosphotyrosine interaction domain containing 1 (PID1)." (PMID 34322395, 2021). "They further recorded a better overall survival in PAX7/FOXO1 positive patients (4-year overall survival was 77%) compared to PAX3/FOXO1 positive ones (4-year overall survival was 52%, p = 0.08), based on the primary tumor evaluation." (PMID 34768955, 2021). "Akt plays a central role in downstream cascade like the activation of proto-oncogenes, such as NF-κB, Wnt, MMP, BCL-2, and VEGF, as well as suppressing tumor-suppressor genes like FOXO1, Bax, Caspase, and Cycs." (PMID 34204873, 2021). "These three ncRNAs connected to DMD are also ‘sponged’ by the PCG FOXO1, which is critical to tumor suppression and apoptosis and presented a putative protective role in colon CRC tumors." (PMID 34178670, 2021). "Among the upregulated and downregulated genes, FOXO1 is a well-known suppressor that promotes the migration and invasion of tumor cells." (PMID 34635635, 2021). "Molecular analysis of excised tumors demonstrated that the treatment reduces tumor growth due to upregulation of forkhead box O1 (FOXO1) and NFKBIA (IκBα), thus activating apoptosis and potentially inhibiting NF-κB activity." (PMID 34572548, 2021). "Subsequently, we co-cultured FOXO1(+) tumor cells with M0 macrophages in the presence of the anti-CSF-1 antibody and found that a percentage of the CD163+/CD68+ macrophages was significantly reduced." (PMID 33052231, 2020). "In conclusion, we report that MMP11 inhibits cell death and promotes tumor growth by activating the IGF1/AKT/FoxO1 pathway in the MMTV-PyMT mouse model of mammary gland tumor." (PMID 32825455, 2020). "Using the high content screening and analysis technology, we found that deletion of FoxO1 in macrophages slows their migration rate and impairs their function to limit tumor cell growth in vitro." (PMID 32973162, 2020). "The results revealed that FOXO1 was frequently upregulated in tumor tissues compared to the non-tumor counterparts (P < 0.05)." (PMID 33052231, 2020). "In tumor cells, FoxO1 is generally considered as a tumor suppressor and upregulation of FoxO1 is beneficial in several types of cancer." (PMID 32973162, 2020). "In summary, FOXO1 is a potential prognostic factor that has a tumor-promoting effect on the infiltration of M2 macrophages and the polarization of M0 macrophages." (PMID 33052231, 2020). "Previous researches implicated the low expression of FOXO1 in CRC, suggesting the potential of FOXO1 as an inhibitor of tumor angiogenesis." (PMID 32364530, 2020). "Digestive malignancies are a well-reviewed cancer type by which FOXO1 exerts a tumor-suppressive role." (PMID 33088284, 2020).
tumor (continued). "An increasing number of studies have confirmed that the re-expression and activation of FOXO1 in tumor cells has great potential in anti-tumor therapy." (PMID 33584800, 2020). "A previous study has shown that quercetin can suppress tumor growth with the induction of FOXO1 activation." (PMID 32964029, 2020). "In previous studies, we found that FoxO1 regulates macrophage polarization in infection and promotes the anti-tumor function of TAMs by upregulating major histocompatibility complex II (MHC-II) expression." (PMID 32973162, 2020). "The forkhead box protein O1 (FOXO1) is considered to be a key tumor suppressor due to its involvement in a broad range of cancer-related functions, including cellular differentiation, apoptosis, cell cycle arrest, and DNA damage." (PMID 32704044, 2020). "The induction of the intermediate expression of FOXO1 can promote tumor proliferation and survival in ALL cell lines." (PMID 33062419, 2020). "The FOXO1 transcription factor is considered a tumor suppressor because of its role in inhibiting cancer cell proliferation and inducing cell apoptosis." (PMID 32929346, 2020). "The FoxO family, which consists of FoxO1, FoxO3, FoxO4, and FoxO6, is known as a tumor suppressor that limits cell proliferation and induces apoptosis." (PMID 32508033, 2020). "The results showed that FOXO1 was downregulated in PCa tumor tissue compared to corresponding surrounding normal tissues." (PMID 32047567, 2020). "Further evidence comes from studies in genetically engineered mouse models (GEMMs), reporting that a complete loss of all six alleles of FOXO1, FOXO3, and FOXO4 dramatically induces the tumor phenotype." (PMID 32629884, 2020). "It will be interesting to better understand each molecule and each cell type regulated by FOXO1 directly in the settings of cancer patients or tumor models." (PMID 33584800, 2020). "Accumulating evidence has shown the paradoxical intrinsic role of the FOXO1 in cancer, which can act as a tumor repressor while also maintaining cancer stem cells." (PMID 33584800, 2020). "FOXO1 is known as a tumor suppressor, and dysregulation of FOXO1 is involved in a variety of tumorigenesis." (PMID 32823589, 2020). "The relevance of FOXO1 to human cancers is further evidenced by the fact that the tumor suppressor functions of FOXO1 are found to be disrupted by many oncogenic pathways." (PMID 32704044, 2020). "Nuclear retention of FOXO1 protein plays a tumor-suppressive role in the prostate, breast, and soft tissue sarcoma." (PMID 32708561, 2020). "On the contrary, as a tumor promoter, FOXO1 and FOXO3 work in tandem in negatively regulating cytotoxicity of CD8+ T and NK cells against tumor cells." (PMID 33396222, 2020). "This phenomenon was further confirmed by the in vivo experiments in which the number of infiltrating M2 macrophages was significantly increased when co-cultured with FOXO1(+) tumor cells." (PMID 33052231, 2020). "Because IL4, IL13, IL10, and CSF-1 are stimuli in M2 differentiation as reported in previous studies 6, 20, we performed qRT-PCR in FOXO1(+) and FOXO1(-) tumor cells to detect the expression of these genes." (PMID 33052231, 2020). "Our study showed that miR-142-3p overexpression facilitated cell proliferation and inhibited FOXO1 protein expression, and knockdown of miR-142-3p inhibited cell proliferation and tumor growth in xenograft mouse models and increased FOXO1 protein expression." (PMID 32047567, 2020). "The subsequent experiments validated that FOXO1(+) tumor cells promoted M0-to-M2 polarization and the migration of M2 macrophages." (PMID 33052231, 2020). "Western blot analysis further indicated that inhibition of miR-183-5p led to a down-regulation in the expression of VEGFA, VEGFAR2, ANG2, PIGF, MMP-2 and MMP-9 along with up-regulated FOXO1 expression in tumor tissues (p < 0.05)." (PMID 32364530, 2020).